EZR (ezrin)
Diseases named in the same sentence as EZR in open-access papers (continued):
Sharing a sentence is not in itself a finding about the gene and the disease.
cervical carcinoma (19 papers, 2011 to 2025). A carcinoma arising from either the exocervical squamous epithelium or the endocervical glandular epithelium. "Further, ezrin was implicated as an EMT regulator and tumor promoter in cervical cancer, and downregulation of ezrin suppressed cervical cancer progression, possibly via the phosphoinositide 3-kinase/Akt pathway." (PMID 28355349, 2017). "In vivo experiments also showed that Ezrin KD reduced the ability of cervical cancer cells to cross the CAM surface and infiltrate the underlying stroma." (PMID 26933912, 2016). "The perinuclear expression of Ezrin protein is significantly associated with the longer survival time of patients with cervical cancer." (PMID 26933912, 2016). "In conclusion, this study showed that the expressions of ezrin and galectin-3 protein may be associated with the development of cervical cancer and their overexpressions may indicate a poor prognosis of this disease." (PMID 28355349, 2017). "The expressions of ezrin and galectin-3, histological grade, depth of stromal invasion, and lymph node metastasis are risk factors affecting the survival rate of patients with cervical cancer." (PMID 28355349, 2017). "Additionally, we found that the strongly positive rate of ezrin protein was significantly associated with the differentiation, lymph node metastatic status and clinical staging of cervical cancers." (PMID 24182314, 2013). "Determination of ezrin expression levels may help to identify high-risk cervical cancer patients and thus aid the selection of appropriate therapies." (PMID 24182314, 2013). "Ezrin and E-cadherin expression profile in cervical cytology samples could be a potential prognostic marker, useful for identifying cervical lesions with a high-risk of progression to cervical cancer." (PMID 29587669, 2018). "In cervical carcinoma, the ezrin protein is highly expressed in all cervical cancer cell lines and tissues compared with normal cervical tissues and predicts poor prognosis in cervical cancer patients." (PMID 38972247, 2024). "In our work, we focused on assessing the effect of the downregulation of the EZR protein level in the context of reducing the metastatic potential of cervical cancer cells." (PMID 39861066, 2024). "The relative mRNA expression levels of ezrin, radixn, and moesin in HeLa cells were higher and that of PD-L1 was moderate among a variety of human cervical cancer cell lines." (PMID 34577118, 2021). "High ezrin expression is correlated with poor prognosis in cervical cancer, and knockdown of ezrin inhibits migration and invasion in cervical cancer cells." (PMID 34885095, 2021). "More than 80% of cervical cancer samples exhibit high Ezrin expression and a decrease in E-cadherin levels, which can be detected using immunohistochemistry and cervical smears." (PMID 33240887, 2020). "From a clinical perspective, cervical cancer patients displaying perinuclear ezrin localization patterns have longer survival times than those with a more diffuse cytoplasmic ezrin localization." (PMID 31936668, 2020). "Due to the high expression of Ezrin, a non-invasive testing method can serve as a milestone for cervical cancer detection, which is crucial for early treatment and a better prognosis in patients with squamous intraepithelial lesions." (PMID 33240887, 2020). "Specifically, Ezrin is increased in cervical cancer cells (SiHa and C33A) when Galectin-1 (LGALS1) is overexpressed." (PMID 33240887, 2020). "Ezrin down-regulation induces Akt phosphorylation, and Ezrin regulates both epithelial-mesenchymal transitions and metastasis in cervical cancer." (PMID 33240887, 2020). "Ezrin promotes cell proliferation through phosphorylation on residue Y145, cell mobility, and migration in cervical cancer cells." (PMID 33240887, 2020). "Another lectin family member, Galectin-3, is also overexpressed along with Ezrin in cervical cancer and both are predictors of poor prognosis in cervical cancer patients." (PMID 33240887, 2020).
cervical carcinoma (continued). "As a migration-related protein, Ezrin is upregulated in cervical cancer and its expression level is associated with advanced metastasis and poor prognosis." (PMID 33240887, 2020). "A recent study has shown that the overexpression of galectin-3 and ezrin had stronger predictive value than either alone in cervical cancer." (PMID 31832021, 2019). "High Ezrin expression was observed in cervical cancer samples (70%), samples with multiple infection by HR-HPV (43%), and samples with integrated viral genome (47%)." (PMID 29587669, 2018). "Recently, it has been reported that Ezrin is overexpressed in cervical cancer or intraepithelial neoplasia (CIN) compared to normal cervical tissue." (PMID 29587669, 2018). "Aberrant expression of Ezrin and E-cadherin has been demonstrated in several cervical cancer cell lines and tumor tissue." (PMID 29587669, 2018). "High Ezrin expression, high percent of nuclear Ezrin and low E-cadherin expression behaved as risk factors for progression to HSIL and cervical cancer." (PMID 29587669, 2018). "We showed that high Ezrin expression and low E-cadherin expression are associated with the risk of progression to HSIL and cervical cancer." (PMID 29587669, 2018). "The mechanisms of ezrin and galectin-3 in the process of development and prognosis for cervical cancer remains to be elucidated, and further research is required." (PMID 28355349, 2017). "The positive expression rates of ezrin and galectin-3 protein in cervical cancer were significantly higher than cervicitis group, and CIN grade I, II, and III groups (all P<0.05)." (PMID 28355349, 2017). "The expressions of ezrin and galectin-3 were correlated with the development of cervical cancer, and overexpressions of those proteins were indicative of poor prognosis in patients with cervical cancer." (PMID 28355349, 2017). "The aim of this study was to explore the correlation of ezrin and galectin-3 expressions with prognosis in cervical cancer." (PMID 28355349, 2017). "Ezrin and galectin-3 expressions in cervical cancer were significantly higher than in normal cervix, cervicitis and CIN (all P<0.05), and expressions in CIN were significantly higher than in normal cervix and cervicitis (both P<0.05)." (PMID 28355349, 2017). "The study found that ezrin expression was related to the development and prognosis of cervical cancer." (PMID 28355349, 2017). "Spearman analysis showed that ezrin expression was positively correlated with galectin-3 expression in cervical cancer (r=0.355, P<0.05)." (PMID 28355349, 2017). "Currently, few studies have focused on the expression of ezrin and galectin-3 protein in cervical cancer." (PMID 28355349, 2017). "Ezrin and galectin-3 expressions in cervical cancer scored – and + were grouped into low expression group, while ++ and +++ were grouped into high expression group." (PMID 28355349, 2017). "The survival rate for cervical cancer patients with high expressions of ezrin and galectin-3 was significantly lower than those with low expressions of the proteins (both P<0.05)." (PMID 28355349, 2017). "Overall, these studies suggest that Ezrin promotes cervical cancer cell proliferation, invasion, and metastasis through EMT." (PMID 26933912, 2016). "We recently reported that Ezrin was over-expressed in cervical cancer, and its expression was closely related to metastasis and poor prognosis." (PMID 26933912, 2016). "Ezrin thus represents a promising target for the development of novel and effective strategies aimed at preventing the progression of cervical cancer." (PMID 26933912, 2016). "We therefore defined specific oncogenic activities of Ezrin in cervical cancer both in vitro and in vivo, and identified the molecular mechanisms whereby Ezrin contributes to cancer invasion and metastasis." (PMID 26933912, 2016). "Ezrin knock-down inhibited anchorage-independent growth, cell migration, and invasion of cervical cancer cell lines in vitro and in vivo." (PMID 26933912, 2016).
cervical carcinoma (continued). "In previous study, we found that Ezrin expression was significantly higher in cervical cancers than in normal cervical epithelia." (PMID 26933912, 2016). "Ezrin protein was highly expressed in all the cervical cancer cell lines, and was significantly increased in cervical cancer tissues compared with the normal tissue sample." (PMID 26933912, 2016). "Ezrin overexpression was closely related with poor differentiation, late stage, and lymph node metastasis, suggesting that Ezrin is frequently over-expressed in cervical cancer." (PMID 26933912, 2016). "Ezrin thus represents a promising new target for the development of novel and effective strategies for preventing the progression of cervical cancer." (PMID 26933912, 2016). "We then investigated the role of Ezrin in cervical cancer cell motility and invasion by wound-healing and transwell assays." (PMID 26933912, 2016). "We detected Ezrin protein expression levels in HeLa, SiHa, C33A, and CaSki cervical cancer cell lines and in three cervical cancer and one normal cervical tissue samples using western blot." (PMID 26933912, 2016). "In accord with these results, we also observed the changes in cervical cancer cell morphology following Ezrin KD." (PMID 26933912, 2016). "In conclusion, Ezrin expression was successfully silenced in cervical cancer cells by RNAi and the down-regulation of Ezrin significantly inhibited proliferation, migration, and invasion of uterine cervical cancer cells through EMT inhibition." (PMID 26933912, 2016). "In this study, we determined the expression of Ezrin in primary cervical cancer tissues and cervical cancer cell lines, including HeLa, SiHa, CaSki and C33A, and also explored the correlation of its expression with EMT markers." (PMID 26933912, 2016). "In previous study, we found that Ezrin expression was significantly higher in cervical cancers than in CIN, CGIN, and normal cervical epithelia." (PMID 26933912, 2016). "In this study, we found that the strongly positive rate of ezrin protein was significantly higher in HPV-infected cervical cancers (82.9%) than in HPV-negative cases (16.7%)." (PMID 24182314, 2013). "For the TNM and FIGO clinical stages, the strongly positive rate of ezrin protein was 96.1% (122/127) in advanced (stages IIB–IV) cervical cancers, but only 49.1% (53/108) in early stage cases (I–IIA) (P<0.05)." (PMID 24182314, 2013). "In conclusion, ezrin is a potential effective predictor of poor prognosis of cervical cancer patients, especially for those with early stage disease." (PMID 24182314, 2013). "Apical membranous distribution of ezrin protein was only observed in normal cervical glands, while perinuclear staining was only observed in cervical cancers." (PMID 24182314, 2013). "Nevertheless, studies to date have not systematically explored the relationship between ezrin and its clinicopathological significance in cervical cancers, particularly the correlation between ezrin expression and human papillomavirus (HPV) infection." (PMID 24182314, 2013). "Strong cytoplasmic and diffuse localization of ezrin were frequently seen in the cervical cancers compared with the normal counterparts." (PMID 24182314, 2013). "Moreover, ezrin expression seems to be a prognostic marker for the progression of cervical premalignant lesions to cervical cancer." (PMID 34885095, 2021). "Ezrin plays a key role in cervical cancer invasion and is a potential prognostic immunomarker." (PMID 33240887, 2020). "EZR is upregulated in a number of diseases, such as breast and cervical cancer, and overexpression of the EZR gene may enhance the metastatic capacity of tumors." (PMID 32596350, 2020). "In addition to cervical cancer, enhanced Ezrin expression is a new, independent prognostic marker in endometrioid carcinoma and is correlated with endometrioid carcinoma stages (FIGO)." (PMID 33240887, 2020).
cervical carcinoma (continued). "One limitation of our study is the small number of samples, and no data are available on the evolution of patients diagnosed with cervical cancer to evaluate the relationship of Ezrin and E-cadherin expression to invasive tumor capacity and survival of patients." (PMID 29587669, 2018). "Ezrin expression is involved in cell migration and invasion in cervical cancer cell lines HeLa and SiHa, it has been suggested that Ezrin could promote cervical cancer progression through regulation of epithelial-mesenchymal transition." (PMID 29587669, 2018). "However, the mechanisms whereby cervical cancer cells acquire the ability to invade nearby tissues and metastasize, and how Ezrin activates EMT in cervical cancer are poorly understood." (PMID 26933912, 2016). "Additionally, we clarified the role of Ezrin in cervical cancer progression by silencing its expression by RNA interference (RNAi)." (PMID 26933912, 2016). "We further determined the role of Ezrin in cervical cancer cell motility by wound-healing assay." (PMID 26933912, 2016). "Then, HPV infection could accelerate ezrin overexpression and lead to invasion and metastasis of cervical cancers." (PMID 24182314, 2013). "Additionally, HPV infection was examined to investigate its correlation with ezrin expression in cervical cancers." (PMID 24182314, 2013). "Aberrant localization and overexpression of ezrin might be an independent effective biomarker for prognostic evaluation of cervical cancers." (PMID 24182314, 2013). "Furthermore, this strongly positive ezrin expression was significantly higher in cervical cancers than in CIN, CGIN, and normal cervical epithelia." (PMID 24182314, 2013). "Interestingly, the strongly positive rate of ezrin protein was significantly higher in HPV-infected cervical cancers (82.9%, 160/193) than in HPV-negative cases (16.7%, 7/42) (P<0.01)." (PMID 24182314, 2013). "In addition, it has been previously indicated that the aberrant localization and overexpression of ezrin could be an independent effective biomarker for prognostic evaluation of early stage cervical cancer." (PMID 28355349, 2017). "Thus, Ezrin KD could effectively inhibit the growth and the proliferation rate of cervical cancer cells in vitro." (PMID 26933912, 2016). "Compared with si-control cells, Ezrin KD markedly reduced the wound-healing abilities of both HeLa and SiHa cells, while migration and invasion assay confirmed that Ezrin was involved in the cell migration and invasion abilities of cervical cancer cells (P < 0.05)." (PMID 26933912, 2016). "Furthermore ezrin overexpression has been reported in cervical cancer biopsies." (PMID 25531390, 2014). "Additionally, ezrin cellular localization was compared with the clinicopathological features of cervical cancers: perinuclear staining of ezrin protein was only observed in cervical SCC and AC (51.4%, 108/210), but not in normal cervix and precancerous disease." (PMID 24182314, 2013). "Additionally, ezrin overexpression was associated with lower 10-year survival rate for patients with early stage cervical cancer, but not for patients with advanced stage." (PMID 24182314, 2013). "In cervical cancer, quercetin potentiated cisplatin-induced apoptosis through coordinated downregulation of MMP2, METTL3, P-Glycoprotein (P-Gp), and ezrin." (PMID 40508204, 2025). "In conclusion, ezrin may function as a scaffold protein for PD-L1; regulate PD-L1 protein expression, possibly via post-translational modification in HeLa cells; and serve as a potential therapeutic target for cervical cancer, improving the current immune checkpoint blockade therapy." (PMID 34577118, 2021). "In another human cervical cancer cell line, OMC4, all three ERM were detected at protein levels, but the relative expression levels of radixin and moesin were lower than that of ezrin." (PMID 34577118, 2021).
cervical carcinoma (continued). "The objective of this study was to analyze the usefulness of Ezrin and E-cadherin expression as prognostic biomarkers for development of HSIL and cervical cancer using liquid-based cytology samples." (PMID 29587669, 2018). "Ezrin is a membrane-cytoskeleton-binding protein recently reported to act as a tumor promoter, and we previously indicated that the aberrant localization and overexpression of Ezrin could be an independent effective biomarker for prognostic evaluation of cervical cancers." (PMID 26933912, 2016). "In this study, we identified Ezrin as a regulator of epithelial-mesenchymal transition (EMT) and metastasis in cervical cancer." (PMID 26933912, 2016). "Another study reported that silencing of some genes in cervical cancer cell lines (SiHa and CaSki) had an effect only on cell migration and invasion but not on cell viability, such as the Ezrin gene." (PMID 38473784, 2024). "In this study, we observed that Ezrin staining was exclusively cytoplasmic in non-tumor cells HaCaT, but was cytoplasmic and perinuclear in cervical cancer cells HeLa and SiHa." (PMID 29587669, 2018). "In cervical cancer cells in vitro, Ezrin expression was higher in HeLa and SiHa cells compared to non-tumor cells HaCaT." (PMID 29587669, 2018). "The results suggest that Ezrin may represent a novel therapeutic target for the reversal of EMT and for preventing metastasis in cervical cancer." (PMID 26933912, 2016). "Consistent with the results of western blot, Ezrin KD significantly increased E-cadherin expression and decreased Vimentin, MMP-2, and β-catenin expression in HeLa and SiHa cells, suggesting that Ezrin KD inhibited EMT in cervical cancer cells in vitro." (PMID 26933912, 2016). "Although podocalyxin has not previously been reported in cervical cancer, it interacts with a protein, ezrin, which has been reported to be upregulated in HR-HPV associated cervical lesions where it was found to co-localise with p16inc." (PMID 25531390, 2014). "Moreover, overexpression of ezrin showed a correlation with the TNM clinical stages, which is higher in advanced (stages IIB–IV) cervical cancers than in early stage cases (I–IIA)." (PMID 24182314, 2013). "Ezrin protein expression was significantly higher in cervical cancers with metastasis (100%, 104/104) than in cases with no metastasis (54.2%, 71/131) (P<0.05)." (PMID 24182314, 2013). "The agents reducing ezrin expression may overcome resistance to PD-1/PD-L1 blockade treatments and may also be a possible adjuvant therapies for the current ICB Abs, possibly by modulating PD-L1 protein expression in human cervical cancers." (PMID 34577118, 2021). "The immunohistochemical method was applied to detect ezrin and galectin-3 expressions in normal cervix tissues (n=30), cervicitis tissues (n=28), cervical intraepithelial neoplasia (CIN) tissues (classified as I-III, n=89), and cervical carcinoma tissues (n=84)." (PMID 28355349, 2017). "However, ezrin overexpression was not related to the histological types of cervical cancers; the strongly positive rate of ezrin protein was 76.8% (96/125) and 70.3% (71/101) in keratinizing and non-keratinizing cervical SCC, respectively (P>0.05)." (PMID 24182314, 2013). "We have previously shown colocalization of ezrin in adherens junctions with N-Cadherin but no expression of E-Cadherin in HPV 18 containing HeLa cervical carcinoma cells, as well as the requirement for Rac1, phosphatidylinositol-4-phosphate 5-kinase (PIPKα) and RhoA for this localization." (PMID 21747943, 2011). "Here, we observed a high Ezrin expression in HSIL and cervical cancer samples compared to non-SIL and HPV negative samples." (PMID 29587669, 2018). "70% of cervical cancer samples show high expression of Ezrin, while 65% of non-SIL HPV (−) samples show low/negative expression of Ezrin." (PMID 29587669, 2018).